ALKBH5 (alkB homolog 5, RNA demethylase)
Diseases named in the same sentence as ALKBH5 in open-access papers (continued):
Sharing a sentence is not in itself a finding about the gene and the disease.
leukemia (continued). "For example, two ALKBH5 inhibitors, 2-{[1-hydroxy-2-oxo-2-phenylethyl] sulfanyl}acetic acid and 4-{[furan-2-yl]methyl}amino-1,2-diazinane-3,6-dione, can effectively inhibit the proliferation of leukemia cells (HL-60, CCRF-CEM, and K562) at low micromolar concentrations." (PMID 40958857, 2025). "Additionally, investigating the impact of ALKBH5 activity on the response of CML cells to current therapies or its influence on leukemia development could shed light on its potential role in the disease process." (PMID 39085650, 2024). "Therefore, the study of ALKBH5 regulation in hematopoiesis could provide potential targets for leukemia treatment in the future." (PMID 37742191, 2023). "Using MLL-AF9 mouse model and a series of leukemia reconstitution experiments in the Alkbh5 conditional knockout mice, we confirmed that Alkbh5 deletion could significantly inhibit the occurrence and development of AML and prolong the survival time of the knockout mice." (PMID 34485297, 2021). "What is more, research has discovered that ALKBH5 was highly expressed in AML cells and that ALKBH5 knockdown diminished the clonogenic ability of AML cells, indicating that ALKBH5 promoted the proliferation of leukemia cells." (PMID 40001461, 2025). "In leukemia stem cells (LSCs), KDM4C enhances ALKBH5 level by elevating chromatin accessibility at the ALKBH5 locus, diminishing H3K9me3 levels, and facilitating the binding of MYB and Pol II." (PMID 40186131, 2025). "ALKBH5-driven 5ʹ UTR m6A demethylation fine-tunes SF3B1 translation to impacts genome stability and leukemia progression." (PMID 37858219, 2023). "FTO and ALKBH5, m6A demethylases, are abnormally expressed in AML and promote tumorigenesis and self-renewal of leukemia stem cells through m6A-dependent regulation of their target mRNAs13–15." (PMID 35217832, 2022). "in AML development revealed ALKBH5, affected by chromatin accessibility through KDM4C, is required in the maintenance of the leukaemia stem cell function by affecting the stability of AXL receptor tyrosine kinase (AXL) transcripts in an m6A‐dependent manner." (PMID 35340126, 2022). "Together, these observations underscore the central function of ALKBH5 in the pathogenesis of leukemia and the self-renewal of leukemia stem cells/leukemia-initiating cells (LSC/LIC), thereby highlighting the role of ALKBH5/N6-methyladenine (m6A) axis for therapeutic potential." (PMID 38501918, 2024). "Further investigation confirmed knockdown of MLL1 and MLL3, but not MLL2 and MLL4, markedly reduces ALKBH5 amounts in leukemia cells." (PMID 35063010, 2022). "Knockout of FTO, but not ALKBH5, significantly suppresses leukemia initiation and progression." (PMID 40435251, 2025). "To determine whether ALKBH5-mediated regulation of energy metabolism is required for leukemogenesis in addition to reduction of TACC3 and AXL1 to limit AML survival, we generated Mll-AF9 mutant leukemia from Cre-rtTA-Alkbh5fl/fl mice." (PMID 37742191, 2023). "In leukemia, some studies displayed a negative correlation between m6A and apoptosis—Bcl-2 overexpression evoked by FTO and ALKBH5 upregulation fights against apoptosis, resulting in resistance of leukemia cells to tyrosine kinase inhibitors (TKIs)." (PMID 35090469, 2022).
Obesity (34 papers, 2014 to 2026). Accumulation of substantial excess body fat. "Among multiple reports, both FTO and ALKBH5 are linked to cancer, FTO is linked to obesity, and ALKBH5 is linked to regulation of the hypoxic response and is a hypoxia-inducible factor target gene, i.e. is upregulated in hypoxia." (PMID 40874592, 2025). "Both enzymes appear to be physiologically important: FTO is associated with obesity, whereas ALKBH5 is involved in fertility." (PMID 24489119, 2014). "A large loop (βIV–V) in ALKBH5 occupies a similar region as the L1 loop of the fat mass and obesity-associated protein that is proposed to confer single-stranded RNA selectivity." (PMID 24489119, 2014). "The expression levels of alpha-ketoglutarate-dependent dioxygenase lab homolog 5 (ALKBH5) protein and fatty mass and obesity-associated genes (FTO) were determined using real-time fluorescence quantification polymerase chain reaction and the western blot technique, respectively." (PMID 36814204, 2023). "FTO and ALKBH5 target mRNA and are associated with obesity and spermatogenesis, respectively." (PMID 36999016, 2023). "Specifically, it is confirmed that HDACi specifically targets HDAC1 and promotes the H3K27ac modification of fat mass‐ and obesity‐associated gene (FTO) and AlkB Homolog 5, RNA Demethylase (ALKBH5), which results in significant activation of FTO and ALKBH5." (PMID 39888307, 2025). "FTO and ALKBH5 are related by sequence and structure, and both are linked to cancer; mutations of the FTO gene are also linked to other diseases, including obesity and brain disorders." (PMID 40874592, 2025). "Hepatocyte-specific deletion of Alkbh5 improves glucose tolerance and mitigates metabolic dysfunction-associated fatty liver disease (MAFLD) in obesity by inhibiting GCGR–cyclic adenosine monophosphate (cAMP) and EGFR–PI3K–AKT–mTORC1 signaling." (PMID 40428320, 2025). "“Writers” like METTL3 and METTL14 add m6A marks, “erasers” such as fat mass and obesity-associated protein (FTO), ALKBH5 remove them, and “readers” including YTHDF1, YTHDC1 recognize the marks, mediating functional outcomes." (PMID 40442779, 2025). "Two cancer-linked human Fe(II) and 2-oxoglutarate (2OG)-dependent oxygenases, the fat mass and obesity associated-protein (FTO), and AlkB human homolog 5 (ALKBH5) catalyse m6A methyl group oxidation." (PMID 40874592, 2025). "First, model limitations: while DIR rats mimic human DICM in ALKBH5 downregulation and ferroptosis, they lack the complexity of human diabetes comorbidities (e.g., obesity, hypertension)." (PMID 40548888, 2025). "In contrast, alpha-ketoglutarate-dependent dioxygenase alkB homolog 5 (ALKBH5) and fat mass and obesity-associated protein (FTO) serve as meticulous erasers, reverting the m6A methylation." (PMID 38577917, 2024). "These methylated groups at RNA can be removed by “erasers” (demethylases) including the fat mass and obesity associated (FTO) and alpha-ketoglutarate-dependent dioxygenase AlkB homolog 5 (ALKBH5)." (PMID 37928272, 2023). "A LP diet supplemented with RML increased (P < 0.05) total m6A levels in the liver and muscle and were accompanied by decreased expression of fat mass and obesity-associated protein (FTO) and alkB homologue 5 (ALKBH5)." (PMID 35821163, 2022). "Obesity-associated gene (FTO) and AlkB homolog 5 RNA demethylase (ALKBH5) serve as erasers to maintain the balance of m6A." (PMID 35461308, 2022). "Fat mass and obesity-associated (FTO) and alkB homologue 5 (ALKBH5) have been identified as demethylase, which promote the dumping of a methyl group from m6A via different mechanisms." (PMID 35821163, 2022). "Further, m6A is dynamically removed by specific demethylases or “erasers” including fat mass and obesity associated (FTO) and AlkB homologue 5 (ALKBH5)." (PMID 34950106, 2021). "In adipose tissue we observed that several m6A regulators (WTAP, VIRMA, YTHDC1 and ALKBH5) correlate with obesity and clinical variables." (PMID 34950106, 2021).
Obesity (continued). "In adipose tissue, we find that subjects with obesity exhibit higher gene expression of ALKBH5 in both fat depots compared to lean individuals." (PMID 34950106, 2021). "The removal of m6A is carried out by 2 demethylases (erasers), Fat mass and obesity-associated gene (FTO), and alkB homolog 5 RNA demethylase (ALKBH5)." (PMID 34324489, 2021). "ALKBH5 shows higher gene expression among individuals with obesity compared to lean subjects which is in line with our results from adipose tissue and thus, adding weight to a potential implication of ALKBH5 in obesity." (PMID 34950106, 2021). "Two human demethylases, the fat mass and obesity-associated (FTO) enzyme and ALKBH5, oxidatively demethylate abundant N6-methyladenosine (m6A) residues in mRNA." (PMID 25452335, 2015). "ALKBH5, as an m6A demethylase, regulates immune responses in diabetes and obesity." (PMID 41527491, 2026). "Mutations/variations in the FTO, but not the ALKBH5, gene are linked to diabetes and obesity, and it is possible that the different product selectivities of the two oxygenases reflect their different biological roles in disease." (PMID 40874592, 2025). "Here, we report that ALKBH5 (AlkB Homolog 5) and FTO (FTO: Fat mass and obesity-associated protein), the two RNA demethylating enzymes, promote the translation of ATF4 mRNA in a transformed liver cell line (Hep3B) treated with the chemotherapeutic drug sorafenib." (PMID 39199320, 2024). "FTO and ALKBH5 primarily demethylate m6A- modified bases, with FTO being the first m6A demethylase identified, showing high demethylation activity for m6A, and ALKBH5 catalyzing the removal of m6A modifications from nuclear RNAs (mainly mRNA), thereby affecting metabolic disease and human obesity." (PMID 36118041, 2022). "RNAs can be methylated by Methyltransferase-like 3(METTL3), Methyltransferase-like 14 (METTL14) (“writers”), and demethylated by the fat mass- and obesity-associated (FTO) protein and the α-ketoglutarate-dependent dioxygenase alkB homolog 5 (ALKBH5) protein (“erasers”)." (PMID 35346019, 2022). "In PBMCs, the eraser ALKBH5 and the readers YTHDF1 and YTHDF3 associate with obesity." (PMID 34950106, 2021). "Furthermore, in human cohorts, the study found that the writers WTAP and VIRMA, the eraser ALKBH5, and reader proteins such as YTHDF1, YTHDF2, and YTHDC1 are associated with obesity by comparing gene expression of m6A regulators in adipose tissue between individuals with obesity and lean controls." (PMID 40428320, 2025). "Moreover, research on inhibitors targeting FTO and ALKBH5 is advancing, with diverse inhibitors identified through high-throughput screening and structural optimization, demonstrating significance in targeting tumors, obesity, and other diseases." (PMID 39192357, 2024).
colon cancer (33 papers, 2020 to 2025). "ALKBH5 downregulation was demonstrated in clinical colon cancer tissue samples, which was tightly associated with distant metastasis and disease stage." (PMID 35063010, 2022). "The demethylation of the lncRNA NEAT1 caused by ALKBH5, an m6A demethylase, promotes the progression of colon cancer." (PMID 35912098, 2022). "CBLL1 was correlated with the N stage, combined with the qPCR results showing that low CBLL1 expression in highly metastatic cell lines, indicates that CBLL1 is related to colon tumor metastasis, while ALKBH5 is associated with T and N stages." (PMID 33670062, 2021). "In both cell lines, we inhibited m6A demethylation by knocking down ALKBH5, an m6A demethylase known to exert tumor-suppressive functions in colon cancer." (PMID 41219359, 2025). "Functionally, the knockdown of ALKBH5 enhanced the proliferation of colon cancer cells, while the overexpression of ALKBH5 suppressed this ability." (PMID 37152066, 2023). "To assess the effect of ALKBH5 on PHF20 mRNA stability, we treated colon cancer cells with actinomycin D and found that ALKBH5 loss improved stability of PHF20 mRNA and prolonged its half‐life." (PMID 35979628, 2022). "Further functional assays confirmed ALKBH5 overexpression inhibits colon cancer cell invasion in vitro and metastasis in experimental animals." (PMID 35063010, 2022). "Compared to normal colon tissues, a great number of m6A regulators with CNV deletions had lower expression in colon cancer tissues (for instance, ALKBH5), and vice versa (e.g., YTHDF1, IGF2BP2, HNRNPA2B1, etc.)." (PMID 36119534, 2022). "ALKBH5 is expressed at low levels in colon cancer; its overexpression inhibits cell metastasis in vivo and cell invasion in vitro, thus suggesting it as a tumor suppressor." (PMID 34079761, 2021). "Previous studies demonstrated that ALKBH5 acted as an oncogene in colon cancer, endometrial cancer, and renal cell carcinoma." (PMID 34496932, 2021). "In colon cancer, ALKBH5 can up-regulate the expression of lncRNA NEAT1 through demethylation modification, thereby promoting tumor progression." (PMID 35070987, 2021). "For example, ALKBH5 was downregulated in human colon cancer tissues and was significantly correlated with distant metastasis." (PMID 34178697, 2021). "ALKBH5 was downregulated in colon cancer tissues, and the overexpression of ALKBH5 greatly reatrained colon cancer cells invasion in vitro and metastasis in vivo." (PMID 32742194, 2020). "Yang and colleagues showed that ALKBH5 was an independent prognostic indicator of overall survival and disease-free survival in colon cancer patients." (PMID 32884942, 2020). "What’s more, decreased expression of ALKBH5 was closely associated with metastasis and American Joint Committee on Cancer (AJCC) stage and acted as an independent prognostic indicator in colon cancer patients." (PMID 32742194, 2020). "ALKBH5 promotes colon cancer progression by decreasing methylation of the NEAT1." (PMID 36032659, 2022). "Furthermore, ALKBH5 was found to significantly inhibit the growth and metastasis of colon cancer cells in vitro and in vivo." (PMID 35979628, 2022). "Next, we explored the effect of ALKBH5 on colon cancer cell function." (PMID 35979628, 2022). "To further determine whether ALKBH5 affects colon cancer cell function in vivo, we established tumour xenograft models." (PMID 35979628, 2022). "Then we carried out rescue experiments to determine whether ALKBH5 had an effect on the biological function of colon cancer cells by regulating PHF20." (PMID 35979628, 2022). "Notably, m6A “reader” ALKBH5 is associated with TNM stage, tumour size, lymph node metastasis, and can be regarded as a prognostic indicator in colon cancer." (PMID 35004679, 2021). "Overexpression of ALKBH5 restrains the invasion and metastasis of colon cancer cells." (PMID 35004679, 2021). "Among them, both two m6A Erasers (FTO and ALKBH5) were downregulated in colon cancer." (PMID 32993738, 2020).
colon cancer (continued). "Moreover, ALKBH5 or NEAT1 gene knockout can partially inhibit the malignant behavior of colon cancer; CircNSUN2 is often upregulated in patients with liver metastasis (LM) from colorectal cancer and is exported from nucleus to cytoplasm in an m6A-dependent manner through binding to YTHDC1." (PMID 35070987, 2021). "In colon cancer cell lines, METTL3 and RBM15 were downregulated, whereas transcript levels of FTO and ALKBH5 were upregulated." (PMID 38665783, 2024). "We initially identified ALKBH5 mRNA expression in five colon cancer cells, and noted that ALKBH5 was elevated in LOVO and RKO cells, compared to other colon cancer cell lines." (PMID 35979628, 2022). "ALKBH5 is involved in mediating methylation reversal, and it is reported that ALKBH5-demethylated lncRNA NEAT1 is overexpressed in GC and colon cancer cells, promoting invasion and metastasis." (PMID 35004679, 2021). "First, we divided 566 colon cancer samples from GSE39582 into two clusters in the same way as performed in TCGA and found the distribution of ALKBH5 and YTHDF1 expression in the two clusters to be quite similar to that in TCGA." (PMID 34079761, 2021).
lung adenocarcinoma (25 papers, 2020 to 2025). A carcinoma that arises from the lung and is characterized by the presence of malignant glandular epithelial cells. "RMRP deficiency in lung adenocarcinoma cell lines suppresses cell proliferation, migration and invasion, and promotes cell apoptosis, mimicking the effects of ALKBH5 inhibition." (PMID 35063010, 2022). "Furthermore, researchers have utilized ALKBH5 to develop risk assessment models, which divide lung adenocarcinoma (LUAD) patients into high-risk and low-risk categories on the basis of the constructed models, emphasizing the potential of ALKBH5 as a marker for cancer prognosis." (PMID 40958857, 2025). "The deletion of ALKBH5 has also been shown to suppress the growth and invasion of lung adenocarcinoma cells." (PMID 40136363, 2025). "The downregulation of ALKBH5 has been identified as a significant method for restraining the proliferation and malignancy of lung adenocarcinoma cells through decreasing the translation efficiency of FOXM1 mediated by m6A modification." (PMID 40136363, 2025). "The abundance of m6A in FOXM1 transcripts was increased after the knockdown of ALKBH5 in lung adenocarcinoma cells, resulting in a reduction of FOXM1 translation and diminished cell proliferation and invasion." (PMID 37007161, 2023). "ALKBH5 knockout in lung adenocarcinoma cells increases m6A abundance in FOXM1 transcript and decreases its translation, leading to reduced cell proliferation and invasion." (PMID 35063010, 2022). "Another study showed that ALKBH5-mediated m6A demethylation of the lncRNA RMRP plays an oncogenic role in lung adenocarcinoma." (PMID 36376862, 2022). "ALKBH5-dependent m6A demethylation of the lncRNA RMRP also has an oncogenic effect in lung adenocarcinoma." (PMID 35063010, 2022). "M6A demethylase ALKBH5 affected the proliferation and invasion of lung adenocarcinoma cells by downregulating m6A modification on FOXM1 (HGNC:3818) mRNA and promoting FOXM1 expression." (PMID 35087827, 2021). "Lastly, ALKBH5 was also closely related with the process of intermittent hypoxia in lung adenocarcinoma cells." (PMID 32742194, 2020). "ALKBH5 was also elevated in lung adenocarcinoma cells under intermittent hypoxia, and the knockdown of ALKBH5 inhibited the proliferation and invasion of lung adenocarcinoma cells via reducing the m6A level of FOXM1." (PMID 32742194, 2020). "While FTO and ALKBH5 affect the proliferation and invasion of lung adenocarcinoma cells via regulating multiple target genes and signaling pathways which are related to malignant tumors." (PMID 33193582, 2020). "For instance, in lung adenocarcinoma, high HNRNPC and IGF2BP3 levels correlate with reduced overall survival, and a six-gene risk signature (KIAA1429, ALKBH5, METTL3, HNRNPC, YTHDC2, and YTHDF1) strongly correlated with various clinical and pathological features." (PMID 36831575, 2023). "Inhibition of RMRP in lung adenocarcinoma cell lines could achieve the same effects of ALKBH5 inhibition, including suppression of the abilities of cell proliferation, migration, and invasion, as well as promotion of apoptosis." (PMID 37007161, 2023). "The ALKBH5-dependent m6A-demethylated lncRNA RMRP is also oncogenic in lung adenocarcinoma." (PMID 37007161, 2023). "In addition to NSCLC, ALKBH5 is elevated in lung adenocarcinoma cells submitted to intermittent hypoxia." (PMID 35063010, 2022). "However, in lung adenocarcinoma, ALKBH5 directly downregulates the m6A modification of FOXM1 mRNA and promotes FOXM1 expression under intermittent hypoxia." (PMID 33428593, 2021). "Moreover, m6A demethylase ALKBH5 expression was elevated in lung adenocarcinoma, and the m6A level was upregulated in forkhead box M1 (FOXM1) mRNA." (PMID 34001850, 2021). "Moreover, ALKBH5 was upregulated in lung adenocarcinoma cells subjected to intermittent hypoxia." (PMID 37007161, 2023).